KDM4C (lysine demethylase 4C)
Description:
Histone demethylase that specifically demethylates 'Lys-9' and 'Lys-36' residues of histone H3, thereby playing a central role in histone code. Does not demethylate histone H3 'Lys-4', H3 'Lys-27' nor H4 'Lys-20'. Demethylates trimethylated H3 'Lys-9' and H3 'Lys-36' residue, while it has no activity on mono- and dimethylated residues. Demethylation of Lys residue generates formaldehyde and succinate.
Synonyms: GASC1; JHDM3C; JMJD2C; KIAA0780; TDRD14C
Tractability: Small molecule: a structure with a bound ligand is known; a high-quality ligand is known; it has a binding pocket of medium quality; it belongs to a druggable protein family. PROTAC: ubiquitination databases record sites on it; a small molecule that binds it is known.
Target class: Epigenetic regulator; Jumonji domain-containing; Eraser; Lysine demethylase
Chemical probes: IOX1 (high quality), PD134170, PD134171, QC6352 (high quality)
Gene: Protein-coding gene on chromosome 9 (6,720,863 to 7,175,648, forward strand). Ensembl gene ENSG00000107077.
Subcellular location: Nucleus
Subcellular location (Human Protein Atlas): Nucleoplasm
Pathways (Reactome):
Chromatin organization: HDMs demethylate histones
Signal Transduction: Activated PKN1 stimulates transcription of AR (androgen receptor) regulated genes KLK2 and KLK3
Gene Ontology:
Molecular function: enzyme binding; histone demethylase activity; histone H3K36 demethylase activity; histone H3K9 demethylase activity; histone H3K9me2/H3K9me3 demethylase activity; nuclear androgen receptor binding; transcription coactivator activity; zinc ion binding
Biological process: androgen receptor signaling pathway; positive regulation of cell population proliferation; positive regulation of transcription by RNA polymerase II; regulation of androgen receptor signaling pathway; chromatin remodeling
Cellular component: chromatin; nucleoplasm; nucleus; pericentric heterochromatin
Genetic constraint (gnomAD): Loss-of-function variants: 58 observed, 88.74 expected, observed/expected ratio (o/e) 0.65, 90% interval 0.53 to 0.81. The synonymous counts are far from expectation, so gnomAD's model fits this gene poorly and the ratio says little. Missense variants: 1,153 observed, 1,064.7 expected, observed/expected ratio (o/e) 1.08, 90% interval 1.03 to 1.14. Synonymous variants: 461 observed, 381.95 expected, observed/expected ratio (o/e) 1.21, 90% interval 1.12 to 1.3.
Homologues: Orthologues: chimpanzee KDM4C (99% identical), macaque KDM4C (98% identical), dog KDM4C (90% identical), guinea pig KDM4C (89% identical), rabbit KDM4C (89% identical), pig KDM4C (86% identical), rat Kdm4c (85% identical), mouse Kdm4c (84% identical), tropical clawed frog kdm4c (64% identical), zebrafish kdm4aa (52% identical), zebrafish kdm4ab (50% identical), Caenorhabditis elegans jmjd-2 (27% identical), and 2 more. Paralogues in human: KDM4B (53% identical), KDM4A (53% identical), KDM4D (25% identical), KDM4F (25% identical), KDM4E (23% identical), KDM5B (20% identical), KDM5A (20% identical), KDM5C (18% identical), KDM5D (18% identical), JARID2 (10% identical).
Diseases named in the same sentence as KDM4C in open-access papers:
KDM4C is named in the same sentence as 83 diseases in open-access papers, as found by Europe PMC text mining. Sharing a sentence is not in itself a finding about the gene and the disease. The quoted sentences say what the papers report.
breast carcinoma (39 papers, 2012 to 2025). "Taken together, these results identified the CTSL–GCLC axis as a key mediator of KDM4C-loss-associated metabolomic and epigenetic remodeling and tumor growth suppression in KDM4C-amplified basal breast cancer." (PMID 40457074, 2025). "In summary, we discovered a unique function of KDM4C specific to KDM4C-amplified basal breast cancer, elucidating the underlying mechanisms and clinical significance." (PMID 40457074, 2025). "To investigate mechanisms underlying KDM4C-loss-mediated growth inhibition, we first performed RNA sequencing (RNA-seq) in four Dox-inducible shKDM4C-expressing basal breast cancer cell lines, including KDM4C-amplified (HCC1954 and SUM149) and KDM4C-non-amplified (HCC1806 and HDQP1) cells." (PMID 40457074, 2025). "Here we identified the GRHL2 transcription factor as a chromatin recruiter of CTSL in KDM4C-amplified basal breast cancer cells." (PMID 40457074, 2025). "In basal‐like breast cancer, inhibition of KDM4C promotes the recruitment of CTSL to chromatin through the transcription factor GRHL2." (PMID 41261048, 2025). "Similar to the pattern of histone cleavage and CTSL activation, KDM4C inhibition or downregulation induced a more pronounced elevation of ROS in KDM4C-amplified basal breast cancer cell lines." (PMID 40457074, 2025). "KDM4C contributes to the progression of breast cancer via its role as an HIF-1α/VEGF signaling co-activator." (PMID 40006021, 2025). "Downregulation of two other KDM4 family members, KDM4A or KDM4B, did not affect the growth of the cell line tested, confirming the specific requirement for KDM4C in basal breast cancer." (PMID 40457074, 2025). "KDM4C regulates cathepsin L-mediated histone H3 N-terminal tail clipping through grainyhead-like 2 (GRHL2) methylation in breast cancer." (PMID 40457074, 2025). "Various studies have shown that KDM4A/JMJD2A, KDM4B/JMJD2B, and/or KDM4C/JMJD2C are overexpressed in breast cancer, colorectal cancer, lung cancer, prostate cancer, and other tumors and are essential for the efficient growth of cancer cells." (PMID 39620228, 2024). "KDM4C knockdown in breast cancer cells has been shown to reduce expression of HIF-1 regulated genes and limit breast tumor growth and metastasis in mice." (PMID 36480544, 2022). "The level of H3K9me3 in cells depended on histone lysine methyltransferases or the opposing demethylases, and various studies have shown that the demethylases KDM4A/JMJD2A, KDM4B/JMJD2B and/or KDM4C/JMJD2C are overexpressed in breast cancer." (PMID 36303253, 2022). "In breast cancer, glioma, and colorectal cancer, KDM4C is involved in biological processes such as tumorigenesis and metastasis." (PMID 36077687, 2022). "For example, KDM4C (also known as GASC1) is amplified in esophageal squamous carcinomas, medulloblastomas and breast cancer." (PMID 24728997, 2014). "Amplification of KDM4C has been reported in breast cancer, oesophageal squamous cell cancer and medulloblastoma and a translocation involving KDM4C is present in mucosa-associated lymphoid tissue lymphomas." (PMID 25145438, 2014). "Breast cancer is associated with multiple histone demethylases, including KDM4A, KDM4B, and KDM4C." (PMID 40006021, 2025). "The gene level of KDM4C is higher in aggressive, basal-like breast cancers." (PMID 31766290, 2019). "In addition, it has been shown in a previous study that the complex of Arid3a, Arid3b, and Kdm4c modulates the chromatin configuration of stemness genes for breast cancer by decreasing H3K9me3." (PMID 30616715, 2019). "The KDM4C (JMJD2C) promotes breast cancer cell transformation and proliferation." (PMID 24858415, 2014). "Hence, KDM4C simulates HIF1α-mediated transactivation of genes that are involved in breast cancer progression." (PMID 24858415, 2014).
breast carcinoma (continued). "As an important DUB, USP9X regulates multi-types of cancer development, such as glioblastoma, lung cancer, colorectal cancer, and breast cancer, through mediating the stability of ALDH1A3, KDM4C, FBW7, CEP131, and Snail1." (PMID 40246814, 2025). "Increased levels of KDM4A and KDM4B have been observed in ERα positive breast cancer cells, while TNBC cells showed an increased level of KDM4C." (PMID 36185256, 2022). "JMJD2C/KDM4C interacts with HIF1A to enhance target gene activation and promote breast cancer progression and metastasis by demethylating H3 lysine 9 near several HIF1A target genes." (PMID 27756687, 2017). "JMJD2C (KDM4C) is induced by HIF-1α to mediate epigenetic regulation of HIF-1α downstream genes involved in metabolic reprogramming and lung metastasis of breast cancer." (PMID 23241400, 2012). "Furthermore, the mRNA levels of KDM4C and GCLC show a significant positive correlation in basal breast cancer in the TCGA cohort, implying coregulation in clinical samples." (PMID 40457074, 2025). "Here we report integrated multi-omic characterization of genetic or pharmacological blockade of KDM4C in KDM4C-amplified and non-amplified basal breast cancer models." (PMID 40457074, 2025). "Several reports indicate that KDM4 family members are over-expressed in various cancers: KDM4A, KDM4B, and KDM4C are over-expressed in prostate cancer; amplification of KDM4B is shown in medulloblastoma; and KDM4C is required for the growth of breast carcinoma and diffuse large B cell lymphoma." (PMID 36975603, 2023). "Other JmjC KDMs involved in breast cancer are KDM4A, KDM4B and, KDM4C." (PMID 36185256, 2022). "Conclusions were that CHD4 coactivates HIF to promote breast tumor growth, and that different mRNAs were also up-regulated in human breast tumors (ZMYND8, KDM4C (JMJD2C), CDK8, CREBBP (CBP), KAT), suggesting the heterogeneity of epigenetic regulation of HIF in breast cancer." (PMID 33981601, 2021). "The KDM4C interacts with HIF-1α and is required for breast cancer progression." (PMID 31766290, 2019). "Its related demethylase, JMJD2C (i.e., KDM4C), is found to be upregulated by HIF-1α and it can serve as a co-activator for HIF-1α which epigenetically modulates metabolic reprogramming and metastasis in breast cancer cells by decreasing H3K9me3 as well." (PMID 26861406, 2016). "To prove a role for CTSL in KDM4C-blockade-induced histone clipping, we deleted CTSL in five basal breast cancer cell lines (three KDM4C-amplified and two non-amplified) using CRISPR–Cas9." (PMID 40457074, 2025). "Based on these analyses, we selected four KDM4C-amplified basal breast cancer cell lines (SUM149, HCC1954, HCC38 and HCC70) and four KDM4C-non-amplified lines (HCC1806, HDQP1, HCC1143 and HCC1569) to assess the functional relevance of KDM4C in basal breast cancer." (PMID 40457074, 2025).
prostate carcinoma (23 papers, 2011 to 2025). A carcinoma that arises from epithelial cells of the prostate gland. "KDM4C overexpression is associated with poor prognosis in prostate cancer and can co-regulate transcriptional activation of the AR." (PMID 34220955, 2021). "The Jumonji C-containing histone lysine demethylase family 4 (KDM4) members, KDM4A‒KDM4C, serve as critical coactivators of AR to promote tumor growth in prostate cancer and are candidate therapeutic targets to overcome AR mutations/alterations-mediated resistance in CRPC." (PMID 35534851, 2022). "Knockout of KDM4C suppresses glycolytic metabolism to inhibit prostate cancer metastasis by inhibiting C-Myc/LDHA signaling." (PMID 37117173, 2023). "The inhibition of KDM4C signaling has been shown to suppress prostate cancer metastasis by interfering with mitochondrial glycolytic metabolism." (PMID 36012577, 2022). "KDM4C knockdown significantly reduced proliferation, colony formation, AR transcriptional activity in prostate cancer cells and inhibited tumor growth of a prostate cancer model in zebrafish." (PMID 34220955, 2021). "KDM4C/JMJD2C is able to demethylate H3K9me3 to promote androgen-dependent growth of prostate cancer cells in androgen-receptor-positive prostate cancers." (PMID 34359832, 2021). "The IHC staining revealed that the intensity of KDM4C protein expression was much higher in prostate carcinoma as compared to paired adjacent normal prostate tissues." (PMID 31766290, 2019). "Among the 99 prostate tumor tissues and 55 adjacent normal prostate tissues analyzed, the mRNA expression level of KDM4C was higher in prostate carcinoma in all four datasets as compared to adjacent normal prostate tissues." (PMID 31766290, 2019). "We further examined the expression levels of KDM4C mRNA in adjacent normal prostate tissues versus prostate carcinoma using Oncomine datasets, including the Arredouani PCa dataset, Grasso PCa dataset, Tomlins PCa dataset, and Varambelly PCa dataset." (PMID 31766290, 2019). "Among these, KDM4C is a histone demethylase and its overexpression has been shown in several cancers including breast, colon and prostate cancers." (PMID 31575031, 2019). "Nonetheless, KDM3A/JMJD1A and KDM4C/JMJD2C were suggested to be hypoxia-inducible genes in kidney and prostate cancer cell lines." (PMID 31739546, 2019). "KDM4C co-localizes with the androgen receptor in prostate carcinomas, and knockdown of KDM4C inhibits transcriptional activation and tumor cell proliferation." (PMID 28416760, 2017). "Regarding the specificity and potency of the in vivo antitumor activity, SD70, a derivative of 8-hydroxyquinoline, specifically inhibits KDM4C (IC50 = 30 μM) and reduces the tumor size in a mouse xenograft model of prostate cancer." (PMID 36975603, 2023).
lung carcinoma (20 papers, 2019 to 2025). "More importantly, we found that MG132 treatment substantially rescued the decline in KDM4C protein caused by USP9X depletion in lung cancer cells, implying that USP9X protects KDM4C from degradation by the proteasome." (PMID 33558705, 2021). "Our results show that KDM4C inhibition brought about increased DNA damage and subdued DNA repair response, rendering lung cancer cells and xenograft tumors more susceptible to IR." (PMID 33558705, 2021). "We further observed that loss of USP9X suppressed the growth and proliferation of lung cancer cells, and these defects were partially restored by overexpression of KDM4C." (PMID 33558705, 2021). "Our clinical data show that KDM4C is overexpressed and associated with poor prognosis in lung cancer." (PMID 33558705, 2021). "To this point, we first constructed KDM4C knockdown lung cancer cells using shRNAs and found that loss of KDM4C inhibited cell proliferation." (PMID 33558705, 2021). "Moreover, KDM4C is negatively associated with CD8+ T cells in lung cancer; transcription sequencing found that KDM4C mainly downregulates the transcript level of CXCL10 and inhibits T cell recruitment to tumors and killing." (PMID 36713412, 2022). "USP9X-mediated KDM4C deubiquitylation promotes lung cancer radioresistance by epigenetically inducing TGF-β2 transcription." (PMID 40246814, 2025). "USP9X-mediated deubiquitination of KDM4C epigenetically induces TGF-β2 transcription to drive radioresistance in lung cancer." (PMID 41488674, 2025). "Overexpression of KDM4C has been shown to promote radioresistance in lung cancer and hepatocellular carcinoma." (PMID 38623585, 2024). "Inhibition of lysine-specific demethylase 4C (KDM4C) augments CD8+ T cell-mediated antitumor immunity in lung carcinoma by activating CXCL10 transcription." (PMID 39346534, 2024). "USP9X enhances the deubiquitination of KDM4C to elevate radioresistance of lung cancer cells by activating the TGF‐β2/Smad signaling." (PMID 39143031, 2024). "KDM4C plays a crucial role in various cancers, including lung cancer, hepatocellular carcinoma, ovarian cancer, and acute myeloid leukemia (AML)." (PMID 38623585, 2024). "We previously uncovered that lysine-specific demethylase 4C (KDM4C) is a regulator of radiosensitivity in lung cancer." (PMID 35121645, 2022). "The aberrantly high expression of KDM4C in lung cancer inhibits CXCL10 transcription by reducing the enrichment of activated histone H3K36me3 at the CXCL10 promoter region, thus decreasing the infiltration and activation of CD8+ T cells." (PMID 35121645, 2022). "In this study, we found that KDM4C inhibition enhanced the transcriptional activity of CXCL10 by increasing the concentration of H3K36me3 at its promoter region in lung cancer." (PMID 35121645, 2022). "In this study, we provided direct evidence that KDM4C is involved in antitumor immunity in lung cancer." (PMID 35121645, 2022). "To evaluate the clinical significance of KDM4C in lung cancer, we first detected the protein level of KDM4C in six human lung cancer cell lines and as predicted, KDM4C protein level was upregulated compared to that in normal human lung epithelial cell HBE." (PMID 33558705, 2021). "More importantly, depletion of USP9X impairs TGF-β2/Smad signaling and radioresistance by destabilizing KDM4C in lung cancer cells." (PMID 33558705, 2021). "In this study, we show that KDM4C is overproduced and predicts poor clinical outcomes in lung cancer patients." (PMID 33558705, 2021). "In this study, we provide substantial evidence that supports the novel role of KDM4C in promoting radioresistance in lung cancer." (PMID 33558705, 2021). "Collectively, these results confirm that USP9X physically and specifically interacts with KDM4C in lung cancer cells." (PMID 33558705, 2021). "Together, these results indicate that USP9X activates TGF-β2/Smad signaling and promotes radioresistance by stabilizing KDM4C in lung cancer cells." (PMID 33558705, 2021).